CD4 (CD4 molecule)
Diseases named in the same sentence as CD4 in open-access papers (continued):
Sharing a sentence is not in itself a finding about the gene and the disease.
tumor (continued). "In the tumour microenvironment of human cancers, CD134 is reported on CD4+ T cells, but its expression on NK cells has not been defined." (PMID 29396470, 2018). "We also preliminary attempted subcutaneous injection of B16F10 cells that we still found significantly increased tumor-infiltrating IFNγ and/or TNFα producing CD4 and CD8 T cells although tumor size was not reduced." (PMID 29403003, 2018). "It seems that HIV status has no impact on the local tumor immune microenvironment, including immune cell subset (CD3, CD4, CD8, and CD68) infiltration or PD-L1 expression." (PMID 29681240, 2018). "Both B2-OKT3 and hNKG2D-OKT3 BiTEs enhanced single-cell polyfunctionality and polyfunctional strength index (PSI) of both CD4+ and CD8+ T cells when activated by K562 tumor cells compared to the Tz47-2C11 negative control." (PMID 30400835, 2018). "We did not see any marked difference of infiltration of CD4, CD8 or FOXP3 positive cells induced by VQ-1 treatment, indicating that VQ-1 neither increases nor decreases the host anti-tumor immune response." (PMID 29492202, 2018). "The count of CD4+ Treg cells (CD4+/CD25+/FoxP3+) was lower in the tumor with HOE642 treatment, with no changes of CD4+ T cells and CD8+ T cells." (PMID 30333031, 2018). "When these T cells in the thymus and spleen were analyzed by flow cytometry, there was no obvious difference in the population of CD4+ and CD8+ thymocytes between WT and Pld2−/− tumor-bearing mice." (PMID 29674728, 2018). "Lymphocytes including CD4+ and CD8+ T cells and CD19+ B cells were also detected in the diffuse infiltrating tumors; however, they were scattered rather than clustered in the tumor tissues, differing from those in nodular tumors." (PMID 30526672, 2018). "Flow cytometry analyses of tumors showed that the combination treatment increased the frequency of CD3+ T cells, including memory/effector CD4 and CD8 T cells, but not regulatory T cells, among tumor-infiltrating leukocytes." (PMID 30500835, 2018). "Generally, CD4+ and CD8+ TIL phenotypes were elevated above naïve levels in pre-treated tumor-bearing rats, except that SLECs were essentially absent; CD4+ and CD8+ Tcm cells were significantly increased." (PMID 29533981, 2018). "The results of the assessment of tumor immune cell populations in tumors showed that anti PD-1 treatment slightly enriched CD8+ and CD4+ T cells, but it did not affect the infiltration of Tregs, MΦ, and DC." (PMID 30117062, 2018). "The MLKL-mRNA-based therapy described here resulted in the clear induction of tumor antigen-specific CD4+ and CD8+ T cell responses without a necessity for tumor sequencing, epitope prediction, and production of a personalized vaccine vector." (PMID 30143632, 2018). "In long-term established GBM cell lines, HLA-G was reported expressed on few tumor cells, where inhibitory signals were directed against CD8+ and CD4+ T cells but not NK cells." (PMID 29967607, 2018). "We found that the M109 tumor does not express PD-L1, does not have CD8+ or CD4+ lymphocyte infiltration in cancer tissues, and is resistant to both anti-PD-1 and anti–PD-L1 treatments." (PMID 30409126, 2018). "In the current study, we observed marked upregulation of BTLA expression on circulating CD4+ but not CD8+ T cells, which is in consistent with our previous studies on BTLA in tumor-infiltrating T cells in HCC patients." (PMID 30116751, 2018). "Curiously, the tumor protection induced by metformin was not altered when CD25+ cells were depleted, suggesting that CD4+Foxp3+IL-10+ T cells induced by metformin treatment do not impair the observed antitumor effect." (PMID 29899823, 2018). "Collectively, these results indicate that activated CD8+ T cells, but not activated CD4+ T cells, tumour cells or human CD8+ T cells, release EVs that downregulate tumour growth and reduce in vitro spheroid formation." (PMID 29382847, 2018).
tumor (continued). "The dual therapy reduces PD-L1+ cells and facilitates non-redundant tumour infiltration of effector CD8+, CD4+ T cells, with increased IFN-γ, ICOS, granzyme B and perforin expression." (PMID 28345650, 2017). "In mouse tumor models, such CD4+ T cells were more efficient in reducing tumor growth than CD8+ T cells, even when the tumor cells were MHC-I positive and MHC-II negative." (PMID 28635644, 2017). "MCA205 tumor cells do not express MHC class II, and CD4+ T cells are not able to directly recognize MCA205 tumor cells, suggesting that APCs are involved in this augmentation." (PMID 28854279, 2017). "Our results support previous findings by showing an increased rate of Treg (either CD4+/CD25+/CD127low or CD4+/CD39+) in TILs compared to non-cancerous mucosa and PBMC of tumor patients." (PMID 28574843, 2017). "Except for MDSCs, the counts of other immune cells, including macrophages, dendritic cells, CD4+ T cells, and CD8+ T cells did not obviously change in the tumor of rmIL-17 treated tumor-bearing mice compared with PBS tumor-bearing mice." (PMID 28002798, 2017). "Our current data revealed that IL-17 was produced primarily by the CD4+ Tcm and CD4+ Tem cells, not by other CD4+ and CD8+ T cell subsets, which is consistent with the reports that 99% of the tumor-infiltrating IL-17 T cells were IL-17 CD4+ (Th17) cells." (PMID 28101811, 2017). "In an immunogenic tumor model, this therapy led to tumor regression and extended survival benefit, which was strictly dependent on CD8+ T cells and IFN-γ, but not CD4+ T cells." (PMID 28555136, 2017). "Younger patients, females and those with negative tumor markers presented increase of CD4+, CD8+CD28+ T cells, and CD4/CD8 ratios in the periphery, which is consistent with a previous study." (PMID 28624781, 2017). "Inhibition of the secondary B16-OVA tumour growth occurred in all mice that previously received CD8+ CTL, with or without co-transferring CD4+ Th1 cells." (PMID 29114389, 2017). "Whereas in the absence of OV infection enhanced tumour production of CCL-5 resulted in Treg recruitment and progression, vvCCL-5 infection led to CD4+ effector T-cell infiltration and a Th2 skewed immune response." (PMID 29157300, 2017). "Because these destructive mechanisms of CD4+ T cells are not affected by the expression level of MHC proteins, they have more advantages in tumor killing than the established effector functions of CD8+ T cells." (PMID 29250133, 2017). "IFN-γ+ cells decreased, whereas Foxp3+ cells increased in the tumours composed of lnc-EGFR, but not lnc-EGFRΔR1, -transduced CD4+ T cells." (PMID 28541302, 2017). "And the expression of these immunosuppressive markers was also high in CD3+CD4+ T cells and CD3+CD8+ T cells in tumor tissues (data not shown)." (PMID 29383101, 2017). "The combination of the CD4+-depleting antibody and mGITRL-FP sustained depletion of regulatory T cells and when combined with mGITRL-FP agonist effects on CD8+ T cells, tumor regression occurred without the need for CD4+ T cells." (PMID 29088720, 2017). "Both markers were upregulated on CD4+ and CD8+ T cells in the presence of BiTE and tumor, but were not upregulated in the absence of BiTE." (PMID 28938530, 2017). "Surprisingly, and in addition to the requirement of CD4 help in achieving maximum CD8 T cell activation, we observed tumor regression in the absence of CD8 T cells." (PMID 28250921, 2017). "The expression of PD-L1 in TE cells and TS cells, in addition to intratumoral PD-1+ lymphocytes did not correlate to previously published tumor tissue expression of lymphocyte markers CD3, CD4, CD8 and CD20." (PMID 28460462, 2017). "We observed improved growth of 67NR and 66cl4 BPTF KD tumors with NK cell depletion (anti-asialo-GM1 mAb), but not with CD8+ or CD4+ T-cell depletion, indicating that NK cells are required for reduced BPTF KD tumor growth." (PMID 28969075, 2017).
tumor (continued). "When evaluating the tumor cells harvested from murine tumor sample, the proportion of CD8(+) T lymphocyte was significantly increased while that of CD4(+) T lymphocyte was not significantly changed." (PMID 29299156, 2017). "This synergistic anti-cancer activity correlated with a significant increase in the number of cytotoxic T lymphocytes recognising tumour cell antigens and was mediated by both CD8+ and NK cells but not CD4+ T cells." (PMID 26751469, 2016). "To this end, we obtained ccRCC patient specimens and sorted prevalent tumor-infiltrating immune populations such as CD8+ T cells (n = 5), NK CD16+ cells (n = 2), CD4+ T cells (n = 3), and macrophages (n = 4) as well as non-immune CD45– cells (n = 1)." (PMID 27855702, 2016). "Non-immunized mice with large tumor burdens had significantly fewer CD8+ T cells and Tregs in their spleens while the numbers of CD4+ T cells were normal." (PMID 27959896, 2016). "Despite the strong reduction in Foxp3+ T cells within the CD4+ T cell population at this stage of tumor growth, the CTL/Treg ratio in the B16SLC35A1 tumor was not different from that in B16scrambled tumors." (PMID 26741508, 2016). "Compared with the blank control group, the CD4+/CD8+ value in negative control group was unchanged, suggesting that tumor bearing did not affect ratio of T-cell subpopulations." (PMID 26753518, 2016). "PD-1 blockade as a monotherapy also showed a significant anti-tumor response and an increased infiltration of CD8 but not CD4 T cells." (PMID 27825115, 2016). "The decrease in tumor growth was dependent on CD8+ T cells; in ACE 10/10 mice, depletion of CD8+ T cells, but not CD4+ T cells, led to rapid tumor growth." (PMID 27018193, 2016). "We have also performed ACTs using CD4+ T cells generated with the same cytokine conditions but in complete DMEM medium (rather than complete advanced-DMEM/F12), and observed no delay of tumor growth in mice treating with these cells (data not shown)." (PMID 27588200, 2016). "Although depletion of NK cells did not alter the proportion of Foxp3+CD4+ T cells within B16SLC35A1 tumors, the CTL/Treg ratio was only in favor of tumor control in NK replete B16SLC35A1." (PMID 26741508, 2016). "We found that C-dextran and PEI increased the percentages of CD4+ and CD8+ T cells in the blood, spleen as well as tumour tissues; while saline or dextran had no such effect." (PMID 27074905, 2016). "CD4+ helper T cells have also been reported to kill target tumor cells, either directly, if the latter expresses MHC II (as the CD4 molecule can only recognize MHC II, not MHC I), or indirectly, when the tumor cell does not express MHC II." (PMID 27843441, 2016). "The CD4/CD8 value, NK cell activity, and PD1 and PDL1 contents in spleens of A-549 tumor-bearing mice were not changed by ZFSC administration." (PMID 27493673, 2016). "In some patients, CD4+ rather than CD8+ T cells, even dominated the tumor-infiltrating T cell response." (PMID 27060000, 2016). "In vivo depletion with neutralizing antibodies revealed that CD4+ and CD8+ T cells but not NK and NKT cells are essential players in combination therapy-mediated tumour rejection." (PMID 27498556, 2016). "We also analyzed CD8+ T cells derived from tumor-infiltrated lymph nodes (TILN) as well as CD4+ TIL and found no such enrichment for VLA-1 expression, suggesting a homing mechanism unique to CD8+ cells in the tumor microenvironment." (PMID 28018343, 2016). "Immunohistochemically, tumor cells are characterized by CD30, ALK, CD5, TIA-1, Granzyme B, EMA positive staining, and CD2, CD3, CD7, CD4, CD8, CD20, CD79a negative staining." (PMID 27612448, 2016). "The CD4/CD8 value and NK cell activity were not affected by ZFSC in HT-1080 tumor-bearing mice (p > 0.05), but PD1 and PDL1 content were significantly lower compared with the control group (p < 0.05)." (PMID 27493673, 2016).
tumor (continued). "Tim‐3 on both peripheral CD4+ T cells and CD8+ T cells were similar among patients with different tumor locations, suggesting that primary tumor sites do not have an effect on Tim‐3 expression." (PMID 27516959, 2016). "RC cells had the following immunophenotype: positive for CD10, CD19, CD20, CD22, CD38, CD43, CD44, and CD79b and negative for CD3, CD4, CD5, CD8, CD11c, CD14, CD30, CD56, and CD200, which was identical to the primary tumor cells." (PMID 26515759, 2015). "In the case of the prophylactic DC-based vaccine we observed only activation of the CD4+ cell population and a slight decrease in the CD8+ component, that was not enough for efficient inhibition of tumor growth." (PMID 26325576, 2015). "Lack of any effect on the levels of CD4+ and CD8+ as well as the T-reg population in the non-tumor bearing mice suggest that dietary 2-DG modulates the immune alterations brought about by growing tumors." (PMID 26135741, 2015). "CD4+ T cells can reject tumors in the absence of CD8+ T cells and provide primary anti-tumor immune responses important for immunosurveillance." (PMID 25992291, 2015). "Previously we and others have published that NK cell depletion by anti-NK1.1 antibodies had no affect on tumor immunity after ACT of TRP-1 CD4+ T cells into lymphopenic hosts." (PMID 26405570, 2015). "Moreover, mice treated with si-A20 and si-A20′ showed a significant increase in CD4+IFN-γ+ and CD8+IFN-γ+ T cells compared with that in control groups, which indicated that the increase in cytotoxic T lymphocytes (CTL) might also contribute to tumor regression." (PMID 26561336, 2015). "In contrast, protein-based vaccines have been reported to induce a stronger response on the generation of CD4+ T cells, but not CD8+ T cells, which is not beneficial for tumor clearance." (PMID 26186692, 2015). "Most immunotherapy strategies utilize self-antigens in a neutral or TH2 cytokine environment, and the vaccine-induced T cells often have a regulatory CD4+CD25+ Foxp3+ profile that can degrade, rather than enhance, the tumor immune response." (PMID 25592450, 2015). "Thus, we propose that the CD4+CD56+ neoplasm may be a tumor counterpart of CD56+ mDCs but not pDCs." (PMID 25779340, 2015). "The efficient priming of E7-specific CD8+ T cells, which is necessary to achieve tumor regression, was made possible by the use of the STxB-vaccine that favors induction of CD8+ T cells, in the absence of a marked CD4 activation." (PMID 26337837, 2015). "We found strongly significant negative correlation between the frequency of both CD4+ and CD8+ T cells in the tumor tissues and the size of the tumors; i.e. the higher the T cells, the lower the tumor size." (PMID 25605488, 2015). "Whole tumor antigens, as opposed to defined tumor-derived peptides and proteins, could represent the ideal source for pulsing DCs as they contain a vast array of immunogenic epitopes to activate both CD4+ and CD8+ tumor-specific T cells to prevent tumor escape." (PMID 26343191, 2015). "Recently, a new subset of CD4+ Tregs that primarily express CD4 and CD69, but not CD25, has been identified in a tumor-bearing mouse model." (PMID 24984576, 2014). "IVS confirmed the presence of polyfunctional CD4+ MAGE-specific T cells, as well as reactivity to other tumor antigens PRAME, survivin, HER2 and Wt1 (not seen or tested for in ex-vivo assays)." (PMID 28837000, 2014). "DLI (CD4− spleen cells) can prevent GVHD, but the tumor growth was not suppressed, indicating that CD4+ cells play important roles in graft-versus-tumor (GVT) and GVHD." (PMID 25364755, 2014). "None of the combinations, including reconstituted CD4/CD8 ratios of the parental T-cell lines (group size n = 4), showed enhanced tumor protection." (PMID 24853673, 2014). "KSY treatment did not promote the recruitment of immune cells (i.e., CD4+ T cells, CD8+ T cells, dendritic cells, NK cells and macrophages) at tumor sites, but Ok-432 indeed elevated local immune cells." (PMID 25510204, 2014).
tumor (continued). "A previous study on the immune response in cervical intra-epithelial neoplasia with and without spontaneous regression reported that CD8(+), CD4(+)/CD25(+) cell ratios and CD138(+) plasma cells were independent predictors of tumor regression." (PMID 24885770, 2014). "CD4+CD25+ Tregs are an important group of negative immunoregulation which induce the immune suppression and immune escape of tumor." (PMID 25788856, 2014). "Eight days after challenge, Luc-DC were cleared from WT and CD4-depleted C57BL/6 mice, whereas CD8β-depleted mice failed to eliminate the MuTuDC lines leading to tumor outgrowth." (PMID 25101081, 2014). "Complete tumor regression, without regrowth, was seen only when cabozantinib was combined with MVA/rF-CEA/TRICOM and required the presence of both CD4+ and CD8+ T cells." (PMID 25388653, 2014). "While providing CD4 stimulation using an HBV-derived peptide is efficient, it does not generate tumor antigen specific CD4 cells." (PMID 24690990, 2014). "On the other hand, CD4+ T cells alone, in the absence of CD8+ T cells, have also been demonstrated to eliminate tumor cells." (PMID 24782871, 2014). "Cyclophosphamide administration, which preferentially removes CD4+CD25+ Tregs but not effector T cells, activated a latent pool of high-avidity tumor antigen-specific CD8+ T cells." (PMID 24637664, 2014). "We showed that pretreatment with sTGF-βR does not decrease the activation status or the number of DCs, CD4+ T cells, or CD8+ T cells in the TDLNs or tumor beds compared to IgG2a." (PMID 23865808, 2013). "Interestingly, Teff/Treg ratio increased for CD4+ and CD8+ suggesting that cyclophosphamide may inhibit Tregs thereby stimulating the effector T cells, functional effect of these data was evidenced by reduced tumor weights when cyclophosphamide was administered before each immunotherapy cycle." (PMID 24216992, 2013). "The equivocation of our results concerning NK cells does not seem to erode the conclusion that CD4+ T cells and not CD8+ T cells played the decisive role in tumor rejection in the present system." (PMID 24348684, 2013). "Gemcitabine treatment of tumor-bearing mice reduced the number of splenic and tumor Gr1+/CD11b+ MDSC without affecting the numbers of CD4+ or CD8+ T cells or NK cells." (PMID 24829747, 2013). "Another important finding is that sorafenib (60 mg·kg−1·day−1) did not significantly change the number of CD4+ and CD8+ T cells in tumor-bearing mice." (PMID 23409093, 2013). "Vaccination of mice with recombinant yeast-brachyury is also shown here to elicit brachyury-specific CD4+ and CD8+ T-cell responses, and to induce anti-tumor immunity in the absence of toxicity." (PMID 24125763, 2013). "Among CD45+ cells, CD8+ T cells and B cells were present at higher frequency in MB49, whereas regulatory CD4+/Foxp3+ cells were more abundant in MB49-I, leading to a very high ratio of cytotoxic to regulatory T lymphocytes in MB49 but not in MB49-I tumours." (PMID 24142880, 2013). "The low levels of IL-10 production by CD4+ and CD8+ T cells stimulated by DC/tumor did not impair the production of IFN-γ (data not shown)." (PMID 23555011, 2013). "However, since Th1 CD4 cell transfer alone did not have therapeutic effect in the EG-7 tumour model, the local concentration of these Th1 cytokines may have been insufficient for direct anti-tumour function, but could still amplify the inflammatory response." (PMID 23717511, 2013). "Although we also observed increased numbers of CD4+ T cells in tumors, depletion of CD8+ T cells, but not CD4+ T cells resulted in accelerated tumor recurrence." (PMID 23671644, 2013). "Moreover, the downmodulation of CD4+CD25+ Treg cells, induced by L-M therapy 11, may favor the therapeutic effect of gemcitabine and contribute to the overall cellular and molecular events leading to tumor eradication and stable antitumor immune response observed in these models." (PMID 24156020, 2013).